CD300H (CD300H molecule (gene/pseudogene))
Description:
May play an important role in innate immunity by mediating a signal for the production of a neutrophil chemoattractant.
Synonyms: CD300Hs
Gene: Protein-coding gene on chromosome 17 (74,560,701 to 74,567,343, reverse strand). Ensembl gene ENSG00000284690.
Subcellular location: Membrane (Isoform 1); Secreted (Isoform 2)
Gene Ontology:
Molecular function: protein binding; protein homodimerization activity; transmembrane signaling receptor activity
Biological process: neutrophil chemotaxis; regulation of innate immune response; signal transduction
Cellular component: extracellular region; plasma membrane; membrane
Genetic constraint (gnomAD): Missense variants: 114 observed, 140.58 expected, observed/expected ratio (o/e) 0.81, 90% interval 0.7 to 0.95. Synonymous variants: 51 observed, 59.57 expected, observed/expected ratio (o/e) 0.86, 90% interval 0.68 to 1.08.
Homologues: Orthologues: chimpanzee CD300H (97% identical), macaque CD300H (92% identical). Paralogues in human: CD300E (44% identical), CD300C (43% identical), CD300A (41% identical), CD300LB (34% identical), CD300LD (34% identical), CD300LF (29% identical), CD300LG (24% identical), FCMR (24% identical), TREM2 (23% identical), FCAMR (22% identical), TMIGD3 (20% identical), PIGR (20% identical), and 1 more.